MIR512-1 (microRNA 512-1)
Synonyms: hsa-mir-512-1; MIRN512-1; mir-512-1
Gene: MicroRNA gene on chromosome 19 (53,666,679 to 53,666,762, forward strand). Ensembl gene ENSG00000207645.
Diseases named in the same sentence as MIR512-1 in open-access papers:
MIR512-1 is named in the same sentence as 1 disease in open-access papers, as found by Europe PMC text mining. Sharing a sentence is not in itself a finding about the gene and the disease. The quoted sentences say what the papers report.
tumours (1 paper, 2024). "We identified MIR182, MIR183, MIR371, MIR373, MIR512-1, MIR512-2, MIR515-1, and MIR520e exhibiting high expression and MIR216b, MIR887, MIR9-2, and MIR9-3 exhibiting low expression in NANOG H/L tumours." (PMID 38693576, 2024).